FAP (fibroblast activation protein alpha)
Diseases named in the same sentence as FAP in open-access papers (continued):
Sharing a sentence is not in itself a finding about the gene and the disease.
gastric cancer (continued). "The table in this file shows the correlations between FAP staining in GCAFs and the clinicopathology of gastric cancer." (PMID 30038550, 2018). "To investigate the in vivo effects of stromal FAP, we examined the tumor promoting effect of FAP in a xenograft gastric cancer nude mouse model." (PMID 30419872, 2018). "Future research should include the effect of FAP in gastric cancer tissues, targeted inhibition of FAP and the possibility of reducing or inhibiting the influence of CAFs on the invasive ability of tumor cells." (PMID 23420648, 2013). "FAP+CAFs were mixed with gastric cancer cell lines and implanted into humanized mice." (PMID 40843362, 2025). "Given the crucial role of immune evasion in gastric cancer resistance to PD-1 monoclonal antibody therapy, we conducted immunohistochemical analysis of FAP+CAF expression levels in tumor tissues from 20 gastric cancer patients who received first-line anti-PD-1 therapy." (PMID 40843362, 2025). "Notably, an elevated presence of FAP+CAFs was observed in gastric cancer tissues exhibiting resistance to PD-1 monoclonal antibody treatment." (PMID 40843362, 2025). "The results showed that FAP+CAFs may impair the efficacy of anti-PD-1 therapy in gastric cancer mice, and that IL-31 blockade can partially restore treatment sensitivity, potentially by alleviating the immunosuppressive effects associated with FAP+CAFs." (PMID 40843362, 2025). "Several studies have shown that the expression of CAF-related markers such as α-smooth muscle actin (α-SMA), fibroblast activation protein (FAP), and platelet-derived growth factor receptor-α (PDGFR-α) can be used as diagnostic and prognostic markers for gastric cancer." (PMID 37404754, 2023). "Conversely, co-transfection of Notch1 inhibitors in P-MSCs with CSF2 knockdown showed rescued the inhibitory effect of CSF inhibitors, including augmented tropism towards gastric cancer cells, enhanced expression of FAP and α-SMA, elevated expression of inflammatory factors GM-CSF, FGF, and PDGF-BB." (PMID 37865637, 2023). "In addition, IGF2BP2 knockdown in P-MSCs significantly suppressed their tropism towards gastric cancer cells and decreased FAP and α-SMA expression in P-MSCs." (PMID 37865637, 2023). "Notably, FAP levels were found to be significantlyhigher in patients with gastric cancer, proposing that FAP levelsmay be a possible pinpointing indicator for gastric cancer." (PMID 39473938, 2023). "Nevertheless, we concentrated on a specific group of patients and verified the clinical values of CAFs biomarkers, including CD10, FAP and GPR77 in locally advanced gastric cancer patients who underwent NCT, and explored the association of these biomarkers with drug resistance and prognosis." (PMID 36387219, 2022). "Finally, the tumor-promoting ability of FAP was investigated by utlizing a xenograft gastric cancer nude mouse model." (PMID 30419872, 2018). "Taken together, stromal FAP promotes GC progression in a xenograft gastric cancer nude mouse model." (PMID 30419872, 2018). "However, the Kaplan–Meier survival curves revealed a significantly poor overall survival in gastric cancer patients with FAP high expression in GCAFs (P = 0.033)." (PMID 30038550, 2018). "Here, our data confirms CD163 in gastric cancer has a positive correlation with Tregs (CD4, CD25 and FOXP3), MDSCs (CD33, CD11b and CD14) and Cafs (FAP), indicating CD163 level is an potential index to monitor the status of tumor associated macrophages, Tregs, MDSCs and Cafs in gastric cancer." (PMID 29152078, 2017). "This study reveals a novel mechanism driving immune evasion in gastric cancer, proposes FAP+CAFs as a potential biomarker for predicting anti-PD-1 therapy resistance, and suggests that targeting the IL-31/STAT6 axis could offer new therapeutic strategies to enhance immunotherapy efficacy." (PMID 40843362, 2025).
gastric cancer (continued). "Our study found that the CAF markers FAP, CD10, and GPR77 were closely associated with the Mandard TRG; the more FAP, CD10, and GPR77 were expressed in CAF, the higher the Mandard TRG score, suggesting that all three labeled CAFs were associated with NCT resistance in gastric cancer." (PMID 37277751, 2023). "In gastric cancer (GC), myCAFs are a key stromal component, marked by high α-SMA, FAP, and Collagen I expression." (PMID 40940809, 2025). "Our findings further demonstrate that IL-31 derived from FAP+CAFs promotes the polarization of naive CD4+ T cells toward the Th2 phenotype, thereby establishing an immunosuppressive TME and facilitating gastric cancer immune evasion." (PMID 40843362, 2025). "Using Western blotting and quantitative PCR, we found that the expression levels of FAP, α-SMA, and S100A4 were significantly higher in CAFs compared to NAFs, confirming the successful extraction of primary CAFs from gastric cancer patients." (PMID 38200591, 2024). "Immunohistochemistry was used to detect the expression of FAP, CD10, and GPR77 in CAFs; the EMT markers (N-cadherin, Snail1, and Twist1) and the CSC markers (ALDH1, CD44, and LGR5) in gastric cancer cells." (PMID 37277751, 2023). "C11_VWF were characterized by co‐expressing marker genes of fibroblasts (COL1A1, FAP, VIM, ACTA2) and endothelial cells (VWF, PECAM1, CLDN5, FLT1, RAMP2), which resembled a subgroup of cells undergoing an EMT transition in gastric cancer." (PMID 38115703, 2023). "Subgroup analysis of high expression of CAFs and stage III–IV gastric cancer showed that FAP (RR, 2.06; 95% CI: 1.14–3.74; P=0.02)was more closely related to stage III-IV gastric cancer than α-SMA (RR, 1.43; 95% CI: 1.07–1.92; P=0.01)." (PMID 36874089, 2023). "In univariate analysis, TRG grading, CAF markers (FAP, CD10), and EMT markers (Snail1, N- cadherin) were related to poorer prognosis in patients with gastric cancer." (PMID 37277751, 2023). "FAP+ CAFs are independent predictive factors to worse tumor regression grade (TRG), that means chemoresistance in gastric cancer." (PMID 37143134, 2023). "Do CAFs expressing FAP, CD10, and GPR77 affect the therapeutic effect of neoadjuvant chemotherapy and prognosis in patients with gastric cancer?" (PMID 37277751, 2023). "Although STF1 and STF3 clusters exhibited upregulation of FAP, ACTA2, and TAGLN, the STF2 cluster exhibited upregulation of only CSPG4, further indicative of distinct CAF sublineages in gastric cancer." (PMID 34642171, 2022). "To assess the clinical relevance of our findings, we mapped FAP and INHBA expression levels across the gastric cancer cohort." (PMID 34642171, 2022). "Eight out of 38 upregulated genes in gastric cancer (ASPN, COL1A1, COL1A2, COL3A1, COL5A1, FAP, FN1, and SPARC) overlapped with the CAF markers list (circos plot on the left)." (PMID 35739492, 2022). "In this study, to investigate the roles of activated GCAFs in gastric cancer patients, we used HE staining combined with PDPN detection to trace GCAFs, and FAP was employed to indicate the activation state of GCAFs." (PMID 30038550, 2018). "Inactivation of NF-κB p65 by PDTC significantly inhibited α-SMA and FAP expression in GC-MSC, and greatly suppressed the capacity of GC-MSC to promote gastric cancer cell HGC-27 colony formation, migration and invasion." (PMID 26934326, 2016). "Previous research has suggested that CAFs in human gastric cancer tissues not only express fibroblast-labeled vimentin, but also the myofibroblast markers SMA and FAP." (PMID 23420648, 2013). "And we also analyzed the correlation between the mRNA level of FAP, SDF-1 and TGF-β1 and the gastric cancer stage." (PMID 20529313, 2010). "Most notably, in the in vivo model where gastric cancer cells were co-injected with FAP+CAFs, we did not include a tumor-only control group without FAP+CAFs." (PMID 40843362, 2025).
gastric cancer (continued). "It is unclear whether CAF expressing FAP, CD10, and GPR77 can influence the NCT efficacy in gastric cancer patients by affecting EMT or stemness in gastric cancer cells." (PMID 37277751, 2023). "Our results revealed that the more CAFs expressing FAP, CD10, and GPR77, the worse the clinicopathological factors of gastric cancer, including higher ypT stage, ypTNM stage, ypN stage, poorer tumor differentiation, and more likely to develop lymphatic vascular invasion and nerve invasion." (PMID 37277751, 2023). "All these findings support our conclusion that CAF expressing FAP, CD10, and GPR77 may lead to drug resistance through the induction of EMT or CSC in gastric cancer cells." (PMID 37277751, 2023). "This study aims to explore whether CAFs expressing FAP, CD10, and GPR77 affect the efficacy of NCT and the prognosis of patients with gastric cancer, and its mechanism." (PMID 37277751, 2023). "We found that FAP, CD10, and GPR77 labled CAF subgroup may promote gastric cancer progression, lead to NCT resistance and poor prognosis by inducing EMT and CSC of gastric cancer cells." (PMID 37277751, 2023). "In this study, we assessed the expressions of FAP, CD10 and GPR77 in CAFs of gastric cancer samples after and before treatment, and evaluated their predictive values on the efficacy of NCT and prognosis in locally advanced gastric cancer patients." (PMID 36387219, 2022). "Expressions of CD10, FAP and GPR77 in CAFs were related to chemoresistance and overall survival, and these biomarkers have predictive values for tumor regression and prognosis in locally advanced gastric cancer patients." (PMID 36387219, 2022). "Moreover, it was shown that the incubation of effector cells with FAP-IL-2v enhanced ADCC against colon and gastric cancer cells by the therapeutic Ab directed against tumor antigens." (PMID 36230765, 2022). "FAP, CD10, and GPR77 labeled CAF subgroup may lead to NCT resistance and poor prognosis by inducing EMT and CSC of gastric cancer cells in locally advanced gastric cancer patients." (PMID 37277751, 2023). "In conclusion, FAP, CD10, and GPR77 labeled CAF subgroup may promote gastric cancer progression, and lead to NCT resistance and poor prognosis by inducing EMT and CSC of gastric cancer cells in locally advanced gastric cancer patients." (PMID 37277751, 2023). "Compared with FAP‐negative CAFs, FAP‐positive CAFs have been found to facilitate tumor growth of gastric cancer in vivo as well as inhibit T‐cell activation and infiltration, which could be responsible for the failure of antitumor immunity." (PMID 37773704, 2023). "In conclusion, the expressions of CD10, FAP and GPR77 in CAFs were related to drug resistance and overall survival, and they could be used as predictors for pathological reaction and prognosis in locally advanced gastric cancer patients." (PMID 36387219, 2022). "However, no relevant study has confirmed that FAP plays a certain role in the early diagnosis of gastric cancer." (PMID 36010886, 2022). "The upregulation of FAP and INHBA in gastric cancers rather than precancerous lesions is a strong indicator of the upregulation of specific mediators in fibroblasts, especially in association with frank cancers." (PMID 38825636, 2024). "Realtime-PCR results also showed significant elevated expression of FAP, SDF-1 and TGF-β1 in gastric cancer tissues compared to normal gastric tissues." (PMID 20529313, 2010). "However, a wide application is expected in the imaging of desmoplastic tumors with high FAP expression—especially in those not detectable by 18F-FDG PET, which include some types of metastatic colorectal tumors (peritoneal carcinomatosis) and hepatic, duodenal, and gastric cancer." (PMID 35631416, 2022).
colon carcinoma (57 papers, 2012 to 2025). "In vivo models of lung cancer and colon cancer also revealed that FAP knockout or drug-based inhibition are associated with decreased microvessel density and slower tumor growth." (PMID 34490078, 2021). "Analyses of a population-based colon cancer cohort demonstrated good prognosis associations of FAP intensity and CD8a density." (PMID 33153037, 2020). "Poor prognosis has been associated with high intratumoral expression of FAP in colon cancer." (PMID 39579201, 2024). "One may also speculate its role in early colon cancer development in patients with FAP mutation." (PMID 31718024, 2019). "In comparing primary tumor site, significantly higher FAP expression was observed in rectal cancers compared to colon cancers (Χ2 test: p = 0.037)." (PMID 39335130, 2024). "The simulations are conducted for the colon cancer indication (intermediate to high FAP expression [median H-Score of 20])." (PMID 39444607, 2024). "Targeting the surface expression of FAP in a murine colon carcinoma model showed increased chemotherapy responsiveness and survival." (PMID 38008819, 2023). "Fibroblast activation protein-α (FAP) gene-modified exosome-like nanovesicles (eNVs-FAP) derived from tumor cells have shown good anti-tumor effects in multiple tumor-bearing mouse models, including colon cancer." (PMID 37553810, 2023). "This revealed the presence of clusters of tumor cells residing in fields of FAP-positive CAFs, similar to normal colon tumor histology." (PMID 37261365, 2023). "A total of 63 tumor samples, 30 samples from normal tissue adjacent to the tumor samples, and 2 positive controls (colon cancer tumor samples) had adequate cellularity for review of H&E slides and quantification of FAP staining." (PMID 37333052, 2023). "To summarize, mIF analysis demonstrated that FAP(+) CAFs are significantly increased at the tumor invasive margin of colon cancer." (PMID 37964075, 2023). "Previous studies in colon cancer demonstrated that patients with high-FAP protein levels in stromal areas of the tumors had significantly shorter OS, independent of the patient’s age40." (PMID 37964075, 2023). "Oral DNA vaccines against FAPα that have demonstrated efficacy in mice models of breast or colon carcinomas are also being tested, along with other immunotoxins targeting FAPα such FAP-PE38." (PMID 36555218, 2022). "In gastric and colon cancers, fibroblast activation protein (FAP) in CAFs leads to more CCL2 and less IFN-γ, eventually damaging the outcome of ICIs therapy, while FAP Inhibition reverses this resistance." (PMID 36120342, 2022). "Stromal FAP expression in human colon cancer samples is a marker of early stage in cancer development and correlated with poor patient outcome." (PMID 32426274, 2020). "This study investigates the prognosis associations of FAP and CD8a in two colon cancer cohorts and, specifically, explores the possibility that the prognostic capacity of CD8-positive cells differs between cases defined by their FAP status." (PMID 33153037, 2020). "In vivo, targeting of FAP-α into an immune-competent murine model of colon cancer decreased blood vessel density and induced fibrillar collagen accumulation." (PMID 32426274, 2020). "This study demonstrated that in colon cancer, CD8 prognosis associations was restricted to the group of tumors with high expression the FAP fibroblast marker." (PMID 33153037, 2020). "HuR inhibition in APC Min mice, a model of FAP and colon cancer, decreased the number of small intestinal tumors, and increased the abundance of Prevotella, Akkermansia, and Lachnospiraceae." (PMID 31620100, 2019). "Some of the most convincing in vivo data on a specific role for CAFs has been demonstrated in a FAP-deficient model of lung and colon cancer, with the demonstration that CAF-derived FAP directly modulates tumor growth and angiogenesis." (PMID 28966935, 2017). "High levels of FAP α in human colon tumors promote tumor growth, progression, metastasis, and recurrence." (PMID 26985769, 2016).
colon carcinoma (continued). "It was previously reported that inhibition of exclusively extracellular proteases with PT-630, a lipophobic amino boronic dipeptide unable to cross the cell membrane, mediates FAP-dependent antitumor activity in a murine colon carcinoma model." (PMID 23554941, 2013). "In a separate study, pharmacological inhibition of the extracellular PPCEs, DPPIV and FAP, appeared to slow tumor growth in lung and colon cancer models." (PMID 23554941, 2013). "FGFR4 expression was significantly positively correlated with that of CXCL10 (Pearson’s R = 0.32; P < 0.001) and CAF markers, including α-SMA (Pearson’s R = 0.43; P < 0.0001), PDGFR-β (Pearson’s R = 0.46; P < 0.0001), and FAP (Pearson’s R = 0.32; P < 0.001) in colon cancer samples." (PMID 40447617, 2025). "Furthermore, FAP, which is selectively expressed in the stromal fibroblasts of colon cancer tumours, has also been identified as a valuable theranostic target." (PMID 38496894, 2024). "We did observe higher expression of FAP in patients with rectal cancers compared to colon cancers." (PMID 39335130, 2024). "Additionally, a distinct subset of CAFs isolated from colon cancer demonstrated increased expression of the FAP protein when co-cultured with colon cancer cell lines." (PMID 38606999, 2024). "Moreover, fibroblast activation protein (FAP) is selectively expressed in the stromal fibroblasts of colon cancer tumours and has received significant consideration as a target for theranostic agents." (PMID 38496894, 2024). "Similar results were also observed in FAP knockout animal models of lung and colon cancers." (PMID 39403603, 2024). "However, in mouse models of transgenic PDAC (KPC mice) and transplantable colon carcinoma (C26 cells), depletion of FAPα+ cells using the Diphtheria Toxin Receptor (DTR) system caused severe systemic toxicity, including cachexia and anaemia." (PMID 36555218, 2022). "Furthermore, it is demonstrated that CD8a density lacks prognostic significance in the FAP intensity-low subset of colon cancer." (PMID 33153037, 2020). "In gastric and colon cancer models, fibroblast activation protein-α (FAP)+ CAFs correlate with an immune suppressive phenotype, with increased CCL2 expression and decreased IFN-gamma and granzyme-B expression, promoting resistance to ICI therapy that is reversed by FAP+ CAF inhibition." (PMID 29970158, 2018). "FAP is also recognized as a useful marker of CAFs, selectively expressed in fibroblasts of several epithelial cancers, and is reported to be related to worse prognosis of pancreatic adenocarcinoma and colon cancer." (PMID 25126747, 2014). "Immunotherapy targeting FAP-α could inhibit tumour growth and increases survival in a murine colon cancer model." (PMID 24885257, 2014). "As an illustration, with a 10-fold increase in FAP-binding affinity versus the reference FAP-4-1BBL molecule, the percentage of patients achieving at least 90% of the maximum pharmacological benefit would be expected to increase from 6% to 39% in the colon cancer indication." (PMID 39444607, 2024). "Similarly, it has shown that DNA vaccine against FAP in the CT26 mouse colon cancer model promoted anti-tumor immune responses by increasing the infiltration of CD8+ T cells and tumor lymphocytes into TME, decreasing the expression levels of collagen in TME, and prolonging survival." (PMID 37316886, 2023). "Furthermore, FAP expression has shown prognostic significance in colon cancer." (PMID 30922247, 2019). "Some studies have analyzed both the intensity and proportion of FAP expression by immunohistochemistry (IHC); these studies suggested that stromal FAP expression promoted tumor prognosis and poor survival in some solid tumor types, including colon cancer and pancreatic adenocarcinoma." (PMID 25775399, 2015). "A study showed that FAP-targeted vaccine effectively enhanced the CAFs-killing effect mediated by CD8+ T cells and increased drug uptake by colon cancer and BC." (PMID 40248695, 2025).